EMP1 (epithelial membrane protein 1)
Diseases named in the same sentence as EMP1 in open-access papers (continued):
Sharing a sentence is not in itself a finding about the gene and the disease.
infection (4 papers, 2018 to 2025). The state of being infected such as from the introduction of a foreign agent such as serum, vaccine, antigenic substance or organism. "The parasite must thus modulate the expression of its proteins; this was seen in parasites having higher Pf EMP1 expression when analyzing controlled infection of Kenyan volunteers having low to moderate exposure to P. falciparum." (PMID 30693273, 2018). "Finally, we showed that loss of emp1 did not prevent phagosomal escape but resulted in a significant reduction in macrophage cytolysis by and cell-to-cell spread of M. marinum during infection." (PMID 37772840, 2023). "We demonstrated that Emp1 is dispensable for ESX-1-dependent secretion and hemolysis and for growth in macrophages during infection." (PMID 37772840, 2023).
EMP1 also shares sentences with these, for which no sentence is quoted: ductal invasive breast carcinoma (2 papers); alcoholism (1); Astrocytoma (1); bipolar disorder (1); bladder tumor (1); Cardiovascular Disease (1); colon cancer (1); dolichostenomelia (1); ectopia lentis (1); endometrial cancer (1); endometrioid ovarian cancers (1); epilepsy (1); fibroepithelial polyp (1); fibrosis (1); germ cell tumor (1); hypophosphatemia (1); hypoplastic left heart syndrome (1); idiopathic pulmonary fibrosis (1); infarction (1); ischemic stroke (1); kidney cancer (1); Marfan syndrome (1); medullary carcinomas (1); nevus (1); nonalcoholic steatohepatitis (1); Obesity (1); ovarian serous tumor (1); Parkinson disease (1); preeclampsia (1); prion disease (1).
A further 4 diseases each share a sentence with EMP1 in 1 paper.